E2F1 (E2F transcription factor 1)
Diseases named in the same sentence as E2F1 in open-access papers (continued):
Sharing a sentence is not in itself a finding about the gene and the disease.
tumor (continued). "Particularly, proliferative targets of MDM2 include the stimulation of E2F1 transcriptional activity, increased E2F1 protein stability, disruption of the Rb-E2F1 complex and inhibition of tumor suppressive functions of Rb." (PMID 28615518, 2017). "In the context of solid tumors, unbalanced E2F1 regulation can lead to the emergence of aggressive tumor cells, which drive cancer progression, resistance to anti-cancer drugs, and the rise of metastatic lesions." (PMID 28775339, 2017). "miR-34a is a tumor-suppressive miRNA which was reported to be capable of suppressing proliferation of a colon cell line by targeting E2F1." (PMID 28293146, 2017). "In this study, integrated analysis revealed that E2F1 expression was significantly increased in GC cases and its expression was positively correlated with the poor pathologic stage, large tumor size and poor prognosis." (PMID 28569791, 2017). "We show here that expression of GASL1 is upregulated by E2F1, and its silencing enhances G1/S transition, cell proliferation and tumor growth in vivo, while its ectopic expression inhibits cell proliferation." (PMID 28423601, 2017). "By mapping gene expression profiles from cancer cell lines displaying the features of EMT transition onto the E2F1 interaction map, we identify a tumor type-specific regulatory core." (PMID 28775339, 2017). "As a tumor suppressor and oncogene, the transcription factor E2F1 is a downstream regulator of the Rb pathway." (PMID 28389657, 2017). "Immunohistochemistry showed that E2F1 and RhoC expression were downregulated in the tumor xenograft tissues of the miR-519d group as compared to the control." (PMID 28146423, 2017). "The immunohistochemistry assay showed that E2F1 and RhoC expression were upregulated in the tumor xenograft tissue from nude mice of the E2F1 group when compared to the control group (P < 0.05)." (PMID 28146423, 2017). "We found that the rs35301225 polymorphism in miR-34a was involved in the occurrence of CRC by acting as a tumor suppressor by down-regulation of tumor-promoting gene E2F1." (PMID 28293146, 2017). "We retrieved three disjoint sub-networks in both tumor entities, which we connected by reviving interactions among the nodes from the E2F1 regulatory network." (PMID 28775339, 2017). "The importance of post-translational modifications for E2F1-regulated functional outcomes has been extensively studied in the context of responses to DNA damage in normal epidermal keratinocytes and various tumour cell types." (PMID 27903963, 2017). "Our integrative network-based methodology, exemplified in the case of E2F1-induced aggressive tumors, has the potential to support the design of cohort- as well as tumor type-specific treatments and ultimately, to fight metastasis and therapy resistance." (PMID 28775339, 2017). "Alterations in the expression of c-MYC and E2F1 affect liver cell ploidy during hepatic growth—after birth and before tumor onset." (PMID 28422055, 2017). "In the nude mouse xenograft model, mice injected with cells stably transfected E2F1 plasmid had a dramatic induction of tumor size (P < 0.05) and faster tumor growth than the control mice (P < 0.05), suggesting that E2F1 promotes tumorigenesis and growth." (PMID 28146423, 2017). "Consistent with the important oncogenic role of E2F1, 7 patients (58%) had at least 2-fold higher expression of E2F1 on tumor tissue compared to paired normal tissue." (PMID 28704519, 2017). "The E2F1 transcription factor induces both proliferation and apoptosis, and is a critical downstream target of the tumor suppressor, RB." (PMID 28423601, 2017). "E2F1 is a well-established promoter of cell proliferation, but its roles in tumour formation and progression are complex, as it can either induce or suppress tumourigenesis." (PMID 27028861, 2016).
tumor (continued). "Previous reports showed that full-length HBx can transcriptionally suppress a subset of important tumor-related genes through enhancing the promoters binding to transcription suppressors like E2F1, SMAD4, YY1 and MAZ." (PMID 27391153, 2016). "The Retinoblastoma protein, Rb, is a tumor suppressor controlling the cell cycle by sequestering several E2F family transcription factors (E2F1-5, hereafter termed E2F)." (PMID 27517489, 2016). "Following the DNA damage, the transcriptional factor E2f1 can be activated as a tumor suppressor and function to inhibit cell proliferation, migration and invasion and induce apoptosis in cancer cells, including A549." (PMID 27994550, 2016). "We find that in normal samples and superficial tumor samples, the activity for the modules of the E2F1, E2F2 and E2F3 target genes is lower than in invasive tumors, as opposed to the target genes of the inhibitory transcription factors E2F4 and E2F6." (PMID 26925094, 2016). "In our previous study, E2F1 was found acting as a tumor driver by activating the transcription of RRM2 in CRC." (PMID 27801665, 2016). "Due to the fact that S18-2 protein levels were elevated in tumor samples, it was of great importance to assess expression of the free E2F1 protein." (PMID 26959119, 2016). "We observed a positive correlation of KIF23 expression with a series of tumor oncogenes, driving cell proliferation, mitosis and metastasis, including E2F transcription factor family (E2F1, E2F1, E2F3) and Rhoc." (PMID 27013586, 2016). "DNMT3B knowck-down also efficiently abolished the phosphorylation status of retinoblastoma (RB) tumour suppressor (p-RB) and induced a parallel slight reduction in E2F1 levels (0.2-fold), this confirming the cell cycle block at G1 phase." (PMID 27764816, 2016). "More importantly, either upregulation of p15 and p27 or downregulation of cyclin D1, CDK4, pRB and E2F1 in tumour cells were also found in xenografted tumours of GC." (PMID 27223087, 2016). "Previous studies have demonstrated that E2F1 can regulate the expression of genes in the cell cycle and act as a tumor suppressor in many types of cancer." (PMID 27322142, 2016). "HIC1 is a tumor suppressor and a transcriptional repressor, which inhibits E2F1 transcription through the recruitment of SWI/SNF complex by a direct interaction with ARID1A." (PMID 27323812, 2016). "As ARID2 repression is closely correlated with cell proliferation and invasiveness, the expression of cell growth and aggressiveness markers Ki-67, E2F1, cyclin D1, and cyclin E1 were then evaluated in tumor tissues." (PMID 27351279, 2016). "In cancer cells, the PI3K-AKT pathway activates E2F1 thereby inactivating tumor suppressive activity." (PMID 27806706, 2016). "An up-regulation of the transcription factor E2F1 has been observed in tumor explants following baicalein treatment." (PMID 27586635, 2016). "The consequence of increased phosphorylation of Rb is the release of Rb-bound E2F1, which is known to induce tumor angiogenesis." (PMID 26784107, 2016). "In our study, expression of S18-2 and free E2F1 proteins increased significantly in tumor tissue compared to NE an HP samples." (PMID 26959119, 2016). "Meanwhile, E2F1 silencing inhibited tumor cell growth and invasiveness, accompanied by markedly decreased binding of E2F1 at CCND1 and CCNE1 gene promoters in ARID2-depleted cells." (PMID 27351279, 2016). "For example, acting as a tumor suppressor, E2F1 methylated by PRMT5 can increase tumor cell growth and inhibit apoptosis." (PMID 27708221, 2016). "The decreased expression of CDK4, CDK6 which were directly inhibited by p16, along with the down-regulated expression of Cyclin D1, E2F1 and pRb confirmed the anti-tumor function of miR-877-3p was the due to p16 activation." (PMID 27429046, 2016).
tumor (continued). "IHC staining demonstrated that upregulation of Tspan5 significantly increased the expression of p27 and p15 but dramatically decreased the expression of cyclin D1, CDK4, pRB and E2F1 in xenograft tumours compared to control tumours (all P<0.001)." (PMID 27223087, 2016). "Important biological consequences of these properties of E2F1 are the maintenance of genomic stability and suppression of tumour development in the epidermis." (PMID 27028861, 2016). "The correlation of Tspan5 expression with the expression of p27, p15, cyclin D1, CDK4, pRB and E2F1 in vivo are also revealed in xenografted tumours." (PMID 27223087, 2016). "The E2F1-increased miR-34c suppressed CRC cell proliferation, supporting a tumour suppressing role of E2F1 in CRC." (PMID 26704889, 2015). "II) E2F1 promoter and Δ24 deletion of viral E1A for efficient and specific replication in tumor cells." (PMID 25714011, 2015). "In that work, a Kaplan-Meier survival plot revealed a significant acceleration in tumor onset when E2F1 was lost and a delay in tumor onset when E2F2 or E2F3 was lost." (PMID 26474282, 2015). "Our present study provides evidence that POH1 deubiquitinates and stabilizes the master transcription factor E2F1 and functions as a tumour-promoting protein in HCCs." (PMID 26510456, 2015). "E2F1 protein was mainly localized in tumour cell nucleus and the co-immunoprecipitation between POH1 and E2F1 was primarily observed in the purified nuclear compartment of the cells." (PMID 26510456, 2015). "Immunohistochemical (IHC) staining revealed reduced E2F1 and Ki67 expression in the xenograft tumours generated from POH1-knockdown cells." (PMID 26510456, 2015). "Ad5/3-E2F-Δ24-GMCSF (CGTG-602) was engineered to contain a tumor specific E2F1 promoter driving an E1 gene deleted at the retinoblastoma protein binding site (“Δ24”)." (PMID 25714011, 2015). "The whole genome-profiles of S6K2 and 4EBP1 high tumours included several genes connected to cell cycle progression, with one of the top genes being the master regulator E2F1." (PMID 26698305, 2015). "These published data based on in vivo models and primary tumor samples support our in vitro finding that E2F1 down regulates SIRT6 transcription and facilitates aerobic glycolysis." (PMID 25816777, 2015). "The E2F1 was also over-expressed in tumor tissues with copy number gains (P < 0.001) and in those without (P = 0.03)." (PMID 26360582, 2015). "Promoters derived from hTERT, survivin, Cox2, AFP and E2F1 gene have been used to drive tumor-specific suicide gene expression." (PMID 26571389, 2015). "Loss of RB/p107 activates E2F function to initiate proliferation; however, E2F1/FOXO apoptosis induction suppresses tumor initiation." (PMID 25907958, 2015). "Although the functions of E2F1 in different cancers are in controversy, there is a consensus that E2F1 plays a tumour suppressing role in CRC." (PMID 26704889, 2015). "Our data shows that E2F1 knockdown increased enhanced leucocytes infiltration into tumor tissues and inhibited tumor growth in vivo." (PMID 24742333, 2014). "The percentage of apoptotic tumor cells was lower in the E2F1 group at 8.82% ± 1.81%, compared with 19.21% ± 2.3% in the GFP group and 22.13% ± 4.6% in the NC group (P < 0.05)." (PMID 25466554, 2014). "E2F1 is a frequently overexpressed protein in human tumor cells that increases the activity of the MDR1 promoter, resulting in higher P-gp levels." (PMID 25466554, 2014). "ICAM-1 staining in DU145/sh-E2F1 tumor tissues was remarkably higher than that in DU145/sh-Con, consistent with the data obtained from Western blot assay." (PMID 24742333, 2014). "E2F1 is thought to act as an oncogene and a tumor suppressor, with its action dependent on the cellular context." (PMID 24465681, 2014). "Knocking down endogenous CTGF expression elevated the activiation of pRB(ser 780), an oncogenic cell cycle regulator including CCND1 and E2F1, and suppressed the expression of tumor suppressors including p15 and p21." (PMID 23755163, 2014).
tumor (continued). "Our studies support a model whereby for E2F1 regulation of tumor immune escape mediated by suppressing ICAM-1." (PMID 24742333, 2014). "We determined the in vivo effects of E2F1-overexpression on tumor size in nude mice, and apoptotic cells in tumor tissues were detected by deoxynucleotidyl transferase-mediated dUTP-biotin nick end labeling and hematoxylin and eosin staining." (PMID 25466554, 2014). "IHC results revealed that E2F1 was strongly positive in SCLC tumor where MMP-16 was highly expressed, indicating that E2F1 was associated with the expression of MMP-16." (PMID 24755270, 2014). "A previous study reported that deregulated E2F1 acts as a driving force in melanoma progression and promotes tumor invasion and metastasis independently from its other cellular activities." (PMID 25466554, 2014). "On the other side, miR-17-92 cluster also can negatively regulate the oncogene E2F1 or MYC to inhibit cell cycle progression as the tumor suppressor gene." (PMID 24722426, 2014). "E2f-1 can induce apoptosis in many types of tumor cells, which has been demonstrated by in vitro gene transfection experiments." (PMID 24393368, 2014). "In this network pRB (retinoblastoma) is a tumour suppressor from the family of pocket proteins, and E2F1 is a transcription factor targeting gene that regulates cell cycle progression." (PMID 25070047, 2014). "We performed Western blot and immunohistochemistry analysis to evaluate the expression of ICAM-1 and E2F1 in the indicated tumor tissues." (PMID 24742333, 2014). "For the elucidation to this phenomenon, e2f-1 can bind directly to promoter of the BIN1 tumor-suppressor gene when DNA is damaged, then trans-activating BIN1 to induce apoptosis." (PMID 24393368, 2014). "Further, we found that reduced CDK4 expression elevated the expression of let-7c, a tumor-suppressive miRNA modulated by E2F1." (PMID 24751144, 2014). "We see that the most central gene is E2F1, which a transcription factor known to have a crucial role in cell cycle and tumor suppression." (PMID 24932011, 2014). "Recently, the relationship between e2f-1 and apoptosis of tumor cells, which plays a complicated role in the generation and progression of many kinds of tumors, has received more attention as revealed by experimental study." (PMID 24393368, 2014). "Keeping in view tumor suppressor role of E2F1 it will be necessary to identify relationship between pRb, E2F1 and regulation of pro-apoptotic genes." (PMID 23773282, 2013). "It has been reported that miR-449a is a direct target of E2F1 and prevents tumor cells from entering S phase by down-regulating E2Fs directly and by inhibiting the activity of E2F transcription factors through the reduction of CDKs." (PMID 23614048, 2013). "In line with the effects of E2Fs on both proliferation and apoptosis, E2F1 functions in vivo in a context-dependent manner as an oncogene or a tumor suppressor." (PMID 24168400, 2013). "The pivotal transcription factor E2F1 which can induce both proliferation and cell death, is a critical downstream target of the tumor suppressor, RB." (PMID 24168400, 2013). "In agreement with previous documents, E2F1-induced G1/S transition triggered tumor cell growth and colony forming which were consistent with larger tumor and higher pT grading." (PMID 24023875, 2013). "As the pRb pathway is functionally inactive in most tumor cells, this can result in deregulation of E2F1 activity, leading to uncontrolled cell proliferation." (PMID 23940755, 2013). "The transcription factor E2F1, previously characterized by the Helin group, is involved in cell cycle control and action of tumor suppressor proteins." (PMID 24039993, 2013). "E2F1 mRNA levels directly correlated with tumor diameter, Fuhrman tumor grade, pT stage, TNM stage grouping and macravascular invasion (MAVI) excluding age and sex." (PMID 24023875, 2013).
tumor (continued). "This had the added value of identifying genes regulated by EBNA3C in non-tumour B cells – independently of p16INK4a, the status of the pRb-E2F1 axis and cell proliferation." (PMID 23436997, 2013). "Given that MMP2, MMP9, vimentin, and ZEB1 were regarded as potential elemental genes implying the pro-metastatic state and higher malignancy of tumor cells, as well as E2F1 downstream target genes, RT-PCR was performed to detect changes in mRNA levels." (PMID 24023875, 2013). "The transcription of genes required for the G1/S transition such as Cyclin E and Cyclin D1 is initiated by E2F1, which is under the control of the Rb tumor suppressor." (PMID 23028659, 2012). "The overexpression of E2F1 leads to tumor growth suppression, which makes it an interesting therapeutic target; however, because it is a master regulator, the precise mechanisms by which it works need to be identified to avoid major side effects." (PMID 22550414, 2012). "In this study, we demonstrated that THU acts on some tumor cell lines to be both A) independently cytotoxic and B) to sensitize gemcitabine cytotoxicity through E2F1 in both CDA-high and CDA-low expressing cells." (PMID 22616006, 2012). "E2F1−/− knockout mice develop tumors with high incident rate, signifying that E2F1 is also engaged with growth inhibitory and tumor suppressive activities." (PMID 22438805, 2012). "Chromatin immunoprecipitation (ChIP) assays were employed to confirm that this combination induced chromatin remodelling of the RASSF1A promoter and increased the occupancy of E2F1 at the promoter of this tumour suppressor gene." (PMID 23251702, 2012). "The levels of E2F1 protein were significantly higher in tumor samples than in non-tumor lung specimens (P = 0.008)." (PMID 23210897, 2012). "EZH2 is a newly identified downstream target of E2F1, which is a major downstream effector of the RB tumor suppressor and has a pivotal role in controlling cell cycle progression." (PMID 22970185, 2012). "The E2F1 TF belongs to the E2F family and displays properties of both an oncogene (induction of proliferation) and tumor suppressor (induction of apoptosis)." (PMID 21272326, 2011). "Benign tumour cells showed a higher expression of p16INK4a pathway members (p16INK4a, E2F1 and cyclin D1) compared with normal salivary gland." (PMID 21917131, 2011). "Our results are indicative that both pRb and E2F1-2-3 act as activators of the detoxification system and have important implications for understanding tumor progression and tumor treatment." (PMID 22022495, 2011). "Western blotting showed that the expression levels of PCNA and E2F1 were increased by 72.0% (P < 0.017) and 90.0% (P < 0.05), respectively, in the tumor tissues of HFD-fed mice relative to controls." (PMID 21834963, 2011). "These earlier studies clearly supported the concept that the pro-proliferative actions of E2F1 were oncogenic whilst the pro-apoptotic actions of E2F1 were tumour suppressive." (PMID 22272113, 2011). "Hypophosphorylated RB inhibits G1/S transition by binding to E2F1 transcription factor and exerts its tumor-suppressor function." (PMID 22174919, 2011). "Further E2F-1 is known to be elevated in many tumor cell lines and responsible for the expression of S phase genes that drives cell cycle progression." (PMID 20196847, 2010). "Earlier studies found that E2F1 transgenic mice showed increases in spontaneous tumor formation in the skin, but they also displayed an inhibition of tumor promotion by O-tetradecanoyl-phorbol-13-acetate (TPA)." (PMID 21106062, 2010). "E2f1 was elected as the target, as its expression plays a key role in cell-cycle progression, besides being up-regulated in most types of tumor." (PMID 21637599, 2010). "Western blot analysis further confirmed the differential expression of E2F1 in the xenograft tumours from both groups." (PMID 20531417, 2010).